LPIN1 (lipin 1)
Diseases named in the same sentence as LPIN1 in open-access papers (continued):
Sharing a sentence is not in itself a finding about the gene and the disease.
prostate carcinoma (6 papers, 2015 to 2025). A carcinoma that arises from epithelial cells of the prostate gland. "We find that two out of five genes (CYP3A5 and LPIN1) with a gene-wise q value equal to zero have previously been associated with prostate cancer, and indeed both genes seem to correspond to a switch in the dominant isoforms." (PMID 28784146, 2017). "The overexpression of lipin-1 was confirmed in situ in prostate cancer and in other cancer types, notably in triple negative breast cancer (TNBC) and in lung adenocarcinomas, where it is associated with poor prognosis." (PMID 33922580, 2021). "The data also suggest a correlation between the expression of Lipin-1 in cells and patients with regards to prostate cancer cell aggressiveness and patient survivability." (PMID 33596934, 2021). "Knockdown of LPIN1 has been shown to reduce the proliferation and migration of breast and prostate cancer cells, suggesting that it functions as an oncogene in these cancers." (PMID 33946554, 2021). "The high expression of lipin-1 in various cancer cell lines as well as its over-expression noticed in about 50 % of high grade prostate cancer samples prompted us to characterize its role in cancer cell phenotype." (PMID 25834103, 2015). "In prostate cancer cells, lipin-1 silencing is correlated with PA accumulation and reduced proliferation, while many reports indicate that increased concentration of PA is often correlated with a proliferative phenotype." (PMID 25834103, 2015). "Lipin-1 was also found highly expressed in prostatic cancers in vivo since 16 out of 30 high-grade human prostate adenocarcinomas were stained with anti-lipin-1 antibodies." (PMID 25834103, 2015). "Here, we show that lipin-1 is up-regulated in several cancer cell lines and overexpressed in 50 % of high grade prostate cancers." (PMID 25834103, 2015). "The knockdown of lipin-1 or the inhibition of its PAP activity by propranolol sensitized breast and prostate cancer cells to the inhibition of mTORC1 by rapamycin, hence providing experimental evidence that lipin-1 represents a potential target for cancer treatments." (PMID 33922580, 2021). "Lipin-1, but not Lipin-2 or − 3, was detected in several prostate cancer cells, and was increased in 22RV1 and PC-3 cell lines." (PMID 33596934, 2021). "Results from GEPIA 2 show expression levels of lipin genes varying between patients with and without prostate cancer, with higher significance in LPIN1 and LPIN3." (PMID 33596934, 2021). "From the studies selected from cBioPortal, alterations in the LPIN1, LPIN2 and LPIN3 genes within prostate cancer, prostate adenocarcinoma, castration-resistant prostate cancer and prostate neuroendocrine carcinoma resulted in amplification being the major form of alteration." (PMID 33596934, 2021). "The alterations in lipin-1, -2 and -3 expression in prostate cancer patients, and correlation between lipin-1 expression and PA and DAG in some select cell lines, suggest that these enzymes may regulate lipid levels in prostate cancer." (PMID 33596934, 2021). "However, this process does not seem to operate in prostate cancer cells depleted in lipin-1." (PMID 25834103, 2015).
hypertriglyceridemia (5 papers, 2008 to 2024). A laboratory test result indicating elevated triglyceride concentration in the blood. "LPIN1 plays a role in abdominal obesity, insulin sensitivity, and hypertriglyceridemia and it is associated to blood pressure regulation, especially in men." (PMID 31333395, 2019). "Mice with lipin 3 haploinsufficiency in their hepatocytes exhibited hypertriglyceridemia, and this haploinsufficiency also induced the overexpression and abnormal distribution of lipin 1 in the cytosol and nucleoplasm." (PMID 37964368, 2023).
liver disease (5 papers, 2015 to 2026). "Several of the splicing factors that are dysregulated in fasted Lpin1–/– liver have been implicated in liver disease." (PMID 34494556, 2021). "The LPIN1 rs13412852 variant has been linked to lipid levels and liver disease in children." (PMID 41751781, 2026).
Sepsis (5 papers, 2021 to 2025). Sepsis is defined as life-threatening organ dysfunction caused by a dysregulated host response to infection. "In conclusion, the present study identified that LPIN1 is statistically associated with mortality in sepsis." (PMID 35222395, 2022). "In conclusion, LPIN1 could become a reliable biomarker for patient survival in sepsis, which is associated with immune and inflammation status." (PMID 35222395, 2022). "The latest study found that the ferroptosis-related gene LPIN1, which is associated with the immune status, could become a reliable biomarker of patient survival in sepsis." (PMID 36117534, 2022). "Expression analysis of four diagnostic biomarkers suggested that the sepsis samples in cluster A had higher expression of SET, LPIN1, and CD74; however, the expression of TXN was remarkably higher in cluster B." (PMID 37346041, 2023). "Four ERRGs, namely SET, LPIN1, TXN, and CD74, have been identified as characteristic diagnostic biomarkers for sepsis." (PMID 37346041, 2023). "In the GSE65682 data set, the LPIN1 expression levels of the normal donor group and the sepsis group were extracted, and the Wilcox test detected the different expressions between the two groups." (PMID 35222395, 2022). "In the sequencing data of the sepsis cell model, LPIN1 also showed a downward trend with the passage of time after LPS stimulation." (PMID 35222395, 2022). "In the GSE65682 data, the area under the ROC curve (AUC) of LPIN1 to significantly distinguish between the normal group and the sepsis group was 0.975." (PMID 35222395, 2022). "It is thus plausible that the TLR4/MyD88/PLD1 axis mediates increases in PA pools that serve as substrates for lipin-1 during the events of macrophage proinflamatory activation and sepsis development described in this study." (PMID 34757442, 2021). "In addition, a nomogram model was developed to explore the diagnostic effectiveness of the expression profiles of SET, LPIN1, TXN, and CD74 for sepsis in both cohorts." (PMID 37346041, 2023). "Therefore, we further verified the mRNA level of LPIN1 after LPS stimulation and found its expression reduced in the sepsis rat model along with NR8383 and RLE cell lines, which were together with increased TNFα and TLR4 expression." (PMID 35222395, 2022). "To confirm these findings, we also found that LPS stimulation could inhibit the expression of LPIN1 in a sepsis rat model." (PMID 35222395, 2022). "The immune infiltration analysis showed that lower expression of LPIN1 was related to macrophage infiltration and could be an independent predictor factor of the survival status in sepsis patients." (PMID 35222395, 2022). "Related pathways of LPIN1 include inflammation and immune response, which indicates that LPIN1 might be a potential therapeutic target for sepsis." (PMID 35222395, 2022). "The expression of LPIN1 in the sepsis group was lower than that of the normal group." (PMID 35222395, 2022). "There was a significant correlation between LPIN1 and the survival of patients with sepsis." (PMID 35222395, 2022). "In our study, however, only LPIN1 is found to be correlated with survival status in sepsis." (PMID 35222395, 2022). "In a future study, we must enroll clinical patients to evaluate whether LPIN1 could become a biomarker for sepsis." (PMID 35222395, 2022). "The bioinformatic analysis allowed us to identify that LPIN1 is a critical gene in sepsis." (PMID 35222395, 2022). "Based on the expression profile of SET, LPIN1, TXN, and CD74, two molecular subgroups of sepsis were obtained with K = 2, with 375 samples in cluster A and 385 samples in cluster B." (PMID 37346041, 2023). "Through PCR analysis, it was found that levels of CD74, LPIN1, and SET were significantly decreased after sepsis in rats, whereas the level of TXN was significantly increased after sepsis in rats, which was consistent with the results of bioinformatics." (PMID 37346041, 2023).
Sepsis (continued). "Another supportive fact for our study was that the mRNA expression levels of CD74, LPIN1, and SET were downregulated in rats with sepsis, whereas TXN was upregulated." (PMID 37346041, 2023). "The expression profiles of SET, LPIN1, and CD74 were significantly lower in the sepsis patients, whereas the expression of TXN was much higher." (PMID 37346041, 2023). "The association analysis illustrated notable relationships between four ERRGs (including SET, LPIN1, TXN, and CD74) and sepsis." (PMID 37346041, 2023). "In the training and test cohorts, we observed that the expression profiles of SET, LPIN1, and CD74 were significantly higher in the healthy group, whereas the expression of TXN was much higher in the sepsis group." (PMID 37346041, 2023). "We demonstrate that TRPC3 is activated by lipin-1-derived DAG during LPS activation, and that blockade of TRPC3 activity ameliorates LPS-driven inflammation and sepsis development in animal models." (PMID 34757442, 2021). "In order to further confirm the correlation between LPIN1 expression and immune cells, the CIBERSORT algorithm was used to analyze the proportion of immune cell infiltration, and a map of 22 immune cells in sepsis samples and their correlation with 22 immune cells were constructed." (PMID 35222395, 2022). "PEBP1 and LPIN1 were both intersected among GSE65682, LPS 2h, and LPS 9h datasets, which indicated that these two genes might have been involved in sepsis-induced ferroptosis." (PMID 35222395, 2022). "Furthermore, we used the survival data of sepsis patients in GSE65682 to perform the survival analysis according to the expression levels of PEBP1 and LPIN1." (PMID 35222395, 2022).
alcoholic steatohepatitis (4 papers, 2016 to 2023). "In the present study, utilizing a mLipin-1KO mouse model, we unveiled an important role of myeloid cell-specific lipin-1 in experimental alcoholic steatohepatitis in mice." (PMID 27666676, 2016). "Lipin-1 is closely related to alcoholic steatohepatitis in adipose tissue by overexpression of adipose-specific lipin-1, which in turn accelerates iron accumulation, causes lipid peroxidation, reduces GSH and GAPDH, and promotes ferroptotic liver damage in mice after alcohol administration." (PMID 37214434, 2023). "In the present study, to determine the effects of loss of lipin-1 in myeloid cells on the development and progression of alcoholic steatohepatitis, we generated a myeloid cell-specific lipin-1 knockout mouse (mLipin-1KO) model utilizing a loxP/Cre recombinase system." (PMID 27666676, 2016).
Hepatic fibrosis (4 papers, 2013 to 2025). The presence of excessive fibrous connective tissue in the liver. "Lipin 1 (LPIN1) rs13412852 polymorphism is related to the severity of liver damage and liver fibrosis progression in children with histological MASLD." (PMID 40507973, 2025). "In fact, one of the most significantly upregulated genes in Adn-Lpin1–/– livers is Col1a1, which clusters to the turquoise model and is a marker of activated stellate cells, the primary mediators of hepatic fibrosis." (PMID 39405118, 2024).
type 2 diabetes (4 papers, 2013 to 2018). "Nevertheless, genetic variation in LPIN1 and LPIN2, and reduced LPIN1 expression levels and PAP1 activity in human adipose tissue have been associated with type 2 diabetes, which suggests a loss of their protective role against lipotoxicity." (PMID 27344312, 2016).
atherosclerosis (3 papers, 2020 to 2023). A disease characterized by the build-up of fatty material and calcium deposition in the arterial wall resulting in partial or complete occlusion of the arterial lumen. "Polymorphisms of LPIN1 are associated with an increased body mass index, type II diabetes, and metabolic syndrome, which are risk factors for atherosclerosis." (PMID 33076403, 2020). "Lipin-1’s enzymatic activity has been implicated in the development of atherosclerosis, as it facilitates the formation of the lipid-laden macrophage phenotype and the production of inflammatory cytokines." (PMID 33076403, 2020). "Intriguingly, lipin 1 has been demonstrated to be an activator of PPARα, suggesting that it constitutes a potential therapeutic target for atherosclerosis." (PMID 37964368, 2023). "The enzymatic activity of lipin-1 in macrophages contributes to the pathogenesis of atherosclerosis, colitis, colon cancer, LPS-induced inflammation, and alcoholic liver disease." (PMID 33077427, 2020). "In research on atherosclerosis, lipin 1 was found to be enriched in macrophage-rich regions in human atherosclerotic plaques, and a study in mice confirmed the promoting activity of lipin 1 in LDL-elicited foam cell formation and pro-inflammatory cytokine production." (PMID 37964368, 2023). "The dual function of lipin-1 may also represent an interesting target for atherosclerosis therapeutics." (PMID 33076403, 2020). "Additionally, in mice, lipin-1 contributes to the pathophysiology of fatty liver disease, colon cancer, and atherosclerosis through the promotion of macrophage pro-inflammatory responses." (PMID 33076403, 2020). "However, there are data that suggest lipin-1 transcriptional co-regulatory activity may be involved in atherosclerosis." (PMID 33076403, 2020).
colon cancer (3 papers, 2020 to 2025). "The lipin-1-mediated production of DAG has also been shown to be implicated in colon cancer." (PMID 33076403, 2020). "Other potential applications include the alleviation of intestinal inflammation-driven colon cancer development and suppression of SARS-CoV-2 replication, conditions affected by loss of lipin 1 PAP activity." (PMID 39577771, 2025). "Meana and colleagues explored the potential role of host lipin-1 in the development of colon cancer." (PMID 33922580, 2021). "Finally, the analysis of several clinical datasets confirmed that high lipin-1 expression is correlated with pro-inflammatory cytokines’ expression and with poorer prognosis in two subtypes of colon cancer." (PMID 33922580, 2021).
lipid metabolism disorders (3 papers, 2018 to 2025). "In addition to lipid metabolic disorders resulting from loss of Nrf1’s function to regulate LPIN1, PGC-1β and other metabolic genes, NASH has a not-yet-identified characteristic of refractory inflammation." (PMID 30562963, 2018).
lung adenocarcinoma (3 papers, 2020 to 2025). A carcinoma that arises from the lung and is characterized by the presence of malignant glandular epithelial cells. "LPIN1 is upregulated in lung adenocarcinoma tumor tissues, and high LPIN1 expression was correlated with poor prognosis of patients with lung adenocarcinoma." (PMID 33194695, 2020). "Similarly, Fan and collaborators observed that lipin-1 silencing decreases proliferation and increases apoptosis in lung adenocarcinoma (LUAD) cell lines, while barely affecting normal control cells." (PMID 33922580, 2021). "In triple‐negative breast cancer and lung adenocarcinoma reduced expression of LPIN1 led to endoplasmic reticulum (ER) stress, thereby activating the inositol‐requiring enzyme‐1 alpha (IRE‐A) pathway." (PMID 40265168, 2025).
prostate adenocarcinoma (3 papers, 2015 to 2021). "The implication of lipin-1 in cancer biology was also suggested by its overexpression in several cancer cell lines and in high-grade prostate adenocarcinomas." (PMID 33922580, 2021). "We previously identified lipin-1 by microarray as a Rac1-regulated gene in the prostate adenocarcinoma cell line PC-3 (personal observation)." (PMID 25834103, 2015).
triple-negative breast carcinoma (3 papers, 2018 to 2021). An invasive breast carcinoma which is negative for expression of estrogen receptor (ER), progesterone receptor (PR), and human epidermal growth factor receptor 2 (HER2). "It was also shown that the expression of lipin 1, an important regulator of FAs, is elevated in triple negative breast cancer cells and prevents EnRS through regulation of phospholipid synthesis." (PMID 30140005, 2018).
Achalasia (2 papers, 2024). A disorder of esophageal motility characterized by the inability of the lower esophageal sphincter to relax during swallowing and by inadequate or lacking peristalsis in the lower half of the body of the esophagus. "Whole-exome sequencing (WES) on achalasia patients and controls revealed an association between the disease and common missense variants rs1705003 (CUTA) and rs1126511 (HLA-DPB1), and three rare variants (CREB5, ESYT3, and LPIN1) in an independent cohort." (PMID 38792545, 2024).
acute kidney injury (2 papers, 2021 to 2026). Sudden and sustained deterioration of the kidney function characterized by decreased glomerular filtration rate, increased serum creatinine or oliguria. "Lipin-1 deficiency is a rare inherited metabolic disorder and a major genetic cause of severe, recurrent rhabdomyolysis in early childhood, carrying a significant risk of acute kidney injury and mortality if unrecognized." (PMID 42220764, 2026).
alcoholic hepatitis (2 papers, 2016 to 2021). Acute hepatitis resulting from ingestion of alcohol. "Our novel data demonstrate that myeloid cell-specific deletion of lipin-1 ameliorated inflammation and alcoholic hepatitis in mice via activation of endocrine adiponectin-FGF15 signaling." (PMID 27666676, 2016).
breast tumors (2 papers, 2020 to 2021). "They observed that lipin-1 expression was correlated with the level of insulin-receptor substrate 1 (IRS1) in breast tumor samples and that lipin-1 co-localizes and directly interacts with IRS1." (PMID 33922580, 2021). "P-Tyr795-lipin-1 and p-Tyr416-Src were markedly increased in human breast tumours compared to adjacent normal tissues." (PMID 33203880, 2020). "We next analysed tyrosine phosphorylation of Src and lipin-1 in 44 human primary breast tumours that were instantaneously processed after surgery." (PMID 33203880, 2020).
Cognitive impairment (2 papers, 2022 to 2023). Abnormal cognition is characterized by deficits in thinking, reasoning, or remembering. "In another research, authors considered that neuroprotection of LPIN1 was associated with inhibition of the PKD/Limk1/Cofilin signaling pathway, and LPIN1 might ameliorate the cognitive impairments in Diabetic encephalopathy (DE) animal models." (PMID 36918862, 2023).
heart failure (2 papers, 2021). Inability of the heart to pump blood at an adequate rate to meet tissue metabolic requirements. "We have previously demonstrated that lipin 1 protein abundance is diminished in mouse models of heart failure coincident with accumulation of PA in the myocardium." (PMID 33986192, 2021). "The expression of LPIN1 is deactivated in human heart failure." (PMID 33986192, 2021). "While the cs-Lpin1–/– mice did not exhibit cardiac dysfunction after TAC surgery, it is probable that a lipin 1 gain-of-function approach might be the better way to test the role of lipin 1 in heart failure, since lipin 1 is deactivated by pathologic stimuli." (PMID 33986192, 2021). "However, mice with cardiac deletion of lipin 1 did not exhibit a propensity to develop heart failure after TAC — a pathologic stimulus that can cause mice with mild cardiomyopathy to develop overt dysfunction." (PMID 33986192, 2021). "The protein abundance of lipin 1 and expression of LPIN1 and LPIN2 mRNA were quantified in heart samples from humans with heart failure, obtained at the time of left ventricular assist device (LVAD) implantation." (PMID 33986192, 2021). "LPIN1 is highly expressed in myocardium, is induced by a physiologic stimulus (β-adrenergic agonism) to increase FAO gene expression, and downregulated by a pathophysiologic stimulus (heart failure or hypertrophy)." (PMID 34722683, 2021).
Hyperinsulinemia (2 papers, 2014 to 2024). An increased concentration of insulin in the blood. "In contrast, on the MASH-inducing diet, the enhanced liver injury exhibited by Adn-Lpin1–/– mice was not accompanied by increased intrahepatic TAG content or hyperinsulinemia." (PMID 39405118, 2024).